CAVIN1 (caveolae associated protein 1)
Diseases named in the same sentence as CAVIN1 in open-access papers (continued):
Sharing a sentence is not in itself a finding about the gene and the disease.
glioma (14 papers, 2020 to 2024). A benign or malignant brain and spinal cord tumor that arises from glial cells (astrocytes, oligodendrocytes, ependymal cells). "The overexpression of polymerase 1 and transcript release factor (PTRF), also known as Cavin1, has been linked to the malignancy grade and worse prognosis in glioma patients." (PMID 38539424, 2024). "Furthermore, overexpression of Cavin1 (polymerase Iand transcript release factor or PTRF) enhances the secretion of pro-tumor type EVs by glioma cells and demonstrates a direct association with the malignancy of glioma patients." (PMID 37700840, 2023). "However, the effects exerted by Cavin1-overexpression on glioma EVs as well as molecular mechanisms underlying such effects remain unclear." (PMID 32550897, 2020). "Our study provides a potential theoretical interpretation for the positive correlation between Cavin1 expression and poor prognosis in glioma patients." (PMID 32550897, 2020). "Further investigation is needed to clarify the critical question of which molecules and pathways besides Caveolin1 are involved in the Cavin1-mediated effect on glioma-derived EVs." (PMID 32550897, 2020). "Our previous study revealed that Cavin1 was positively correlated with malignancy grades of glioma patients, and that overexpressing Cavin1 in glioma cells enhanced the malignancy of nearby glioma cells via EVs." (PMID 32550897, 2020). "Polymerase I and transcript release factor (PTRF), also known as Cavin1, has previously been described as a critical biomarker in both glioma and serum exosomes." (PMID 32272554, 2020). "To gain insight into the role of Cavin1 in inter-glioma cell communication in vivo, we established an intracranial mixed-glioma model." (PMID 32550897, 2020). "Here, we report on an essential role played by Cavin1-Caveolin1 binding in regulating glioma EV secretion and function." (PMID 32550897, 2020). "Cavin1 expression in glioma cells increased the malignancy of nearby cells via EVs in vitro and in vivo, and Cavin1 was positively correlated with tumor grades and poor prognoses in glioma patients." (PMID 32550897, 2020). "Compared with the vCavin1, Cavin1 in glioma cells significantly increased EV secretion, uptake and homing ability." (PMID 32550897, 2020). "A previous study of ours revealed that Cavin1 was involved in EV mediated communication among glioma cells." (PMID 32550897, 2020). "The results of the current study indicated that both M1 and M2 markers were elevated in Cavin1 overexpression group, suggesting that Cavin1 overexpressing glioma cells exerted a general activating effect on microglia/macrophages via EVs." (PMID 32550897, 2020). "Polymerase I and transcriptional release factor (PTRF) known as Cavin1 in serum EVs contributed to the detection of gliomas were hopeful biomarkers and may be a treatment target point for GBM." (PMID 33670924, 2021). "However, the current study revealed that Cavin1 not only enhanced EV production in the glioma cell lines, U87 and GL261, but also affected EV cargo and function." (PMID 32550897, 2020). "This study revealed a hitherto unknown role of Cavin1 in EV-mediated communication not only between glioma cells, but also between glioma cells and microglia." (PMID 32550897, 2020). "Moreover, we demonstrated that interaction between Cavin1 and Caveolin1 displayed a significant role in EV production and function in glioma cells." (PMID 32550897, 2020). "Moreover, our findings indicated a promising therapeutic target for those gliomas that express high levels of Cavin1." (PMID 32550897, 2020). "This study provided more evidence for enhancement of glioma malignancy by Cavin1 overexpression." (PMID 32550897, 2020). "EVs expressing Cavin1 promoted glioma growth in vitro and in vivo." (PMID 32550897, 2020). "In addition, glioma EVs expressing Cavin1 enhanced proliferation of nearby glioma cells and exerted recruiting and activating effects on microglia." (PMID 32550897, 2020).
glioma (continued). "Therefore, the dynamic activation state and function of these glioma-TAMs, and the detailed roles played by Cavin1-expressing glioma-EVs in TAM reprogramming need further investigation." (PMID 32550897, 2020). "In addition, Cavin1 expressing murine glioma cells recruited and activated microglia via EVs." (PMID 32550897, 2020). "Furthermore, increased accumulation of Cavin1-overexpressing U87-EVs in glioma might suggest that the permeability of U87-C-EVs across the blood-brain barrier (BBB) was elevated." (PMID 32550897, 2020). "Hence, we investigated whether Cavin1 expression affected EV-mediated communication between glioma cells and microglia." (PMID 32550897, 2020). "In gliomas, PTRF/Cavin-1 not only serves as a marker for patient prognosis, but also promotes malignant behavior by affecting tumor cell endocytosis and exocytosis, reprogramming tumor lipid metabolism, and remodeling the extracellular matrix of tumors." (PMID 38111705, 2023). "Apart from the B2M was abnormally upregulated, other recent reported molecules such as NUSAP1, Paxillin, CAVIN1, and PARP9 also overexpressed in glioma tissues." (PMID 33960680, 2021). "However, whether there is direct interaction between Cavin1 and Caveolin1 remains controversial, and the role interaction between Cavin1 and Caveolin1 plays in glioma biology has not been clarified." (PMID 32550897, 2020). "In conclusion, we demonstrated that Cavin1 overexpression in glioma cell lines, U87 and GL261, not only enhanced EV production, uptake and homing ability, but also promoted EV mediated proliferation of nearby glioma cells and the recruitment and activation of microglia/macrophages." (PMID 32550897, 2020).
cardiac arrhythmia (11 papers, 2012 to 2025). Any disturbances of the normal rhythmic beating of the heart or MYOCARDIAL CONTRACTION. "Congenital generalized lipodystrophy type 4 (CGL4) is a rare, autosomal recessive disorder caused by mutations in the CAVIN1 gene and is characterized by unique features such as gastrointestinal dysmotility, myopathy, and arrhythmias." (PMID 40718185, 2025). "Furthermore, in patients with congenital generalized lipodystrophy with muscle rippling (CGL4) who have homozygous PTRF/Cavin-1 mutations, long-QT syndrome and fatal cardiac arrhythmia were observed." (PMID 27612189, 2016). "Additionally, long-QT syndrome and fatal cardiac arrhythmia are observed in patients with CGL4 who have homozygous PTRF/Cavin-1 mutations." (PMID 27612189, 2016). "Cavin-1 (PTRF) mutations give rise to a combined state of lipo- and muscular dystrophy and increase the risk of cardiac arrhythmias." (PMID 26244347, 2015). "Indeed, the majority of dystrophinopathy patients have arrhythmias, long QT syndrome and contractile dysfunction, and therefore overlap in phenotype with patients with mutations in cypher, CRYAB, Ahnak1, or Cavin-1." (PMID 22937058, 2012).
congenital generalized lipodystrophy type 4 (10 papers, 2010 to 2025). Any congenital generalized lipodystrophy in which the cause of the disease is a mutation in the CAVIN1 gene. "Congenital generalized lipodystrophy type 4 (CGL4) is a rare form of lipodystrophy associated with a loss-of-function mutation in the CAVIN1 gene." (PMID 39874659, 2025). "Mutations in the PTRF/Cavin-1 gene cause congenital generalized lipodystrophy type 4 (CGL4) associated with myopathy." (PMID 27612189, 2016). "Mutations in the PTRF gene, coding for cavin-1, cause congenital generalized lipodystrophy type 4 (CGL4) associated with myopathy." (PMID 24024685, 2013). "Congenital generalized lipodystrophy type 4 (CGL4) is a rare disease caused by mutations in the gene CAVIN1, also known as polymerase I and transcript release factor, with systemic loss of body fat and predisposition for diabetes mellitus, hypertriglyceridemia, and hepatic steatosis." (PMID 33042738, 2020).
generalized lipodystrophy (10 papers, 2010 to 2024). Almost complete absence of subcutaneous and/or visceral adipose tissue. "Several inactivating frameshift mutations within exon 2 of the cavin-1 gene that result in the production of altered cavin-1 proteins have been identified in patients with general lipodystrophy, muscular dystrophy, and insulin resistance." (PMID 29330478, 2018). "The four main forms of Congenital Generalized Lipodystrophy, referred to as CGL1 to CGL4, are due to pathogenic variants in AGPAT2, BSCL2, CAV1, and CAVIN1/PTRF genes, respectively." (PMID 38678257, 2024). "Mutations in human CAVIN1 (PTRF) have been reported to cause MD and generalized lipodystrophy, defects that are likely secondary to caveolae disruption." (PMID 27294373, 2016).
muscular dystrophy (10 papers, 2012 to 2023). Muscular dystrophy (MD) refers to a group of more than 30 genetic diseases characterized by progressive weakness and degeneration of the skeletal muscles that control movement. "One aspect that merits highlighting is that loss-of-function mutations within the muscle-specific caveolin isoform CAV3 or CAVIN1 causes muscular dystrophy." (PMID 30595521, 2019). "The Hippo pathway is a potent regulator of muscle cells, and intriguingly, there are overlapping gene sets between those upregulated in muscular dystrophy, caused by CAVIN1 or CAV3 mutations, and those driven by deregulation of muscular YAP/TAZ-TEAD transcription." (PMID 30595521, 2019). "Formation of caveolae depends on caveolins (CAV1-CAV3) and cavins (CAVIN1, CAVIN2, CAVIN3, CAVIN4) and mutations that cause loss of caveolae give rise to muscular dystrophy, lipodystrophy and cardiac rhythm disturbances." (PMID 28542204, 2017). "Cavin-1 is expressed in several tissues, including muscles, thus resulting, when dysfunctional, in a clinical phenotype characterized by the absence of adipose tissue and muscular dystrophy." (PMID 37501786, 2023). "PTRF/Cavin-1-null (PTRF−/−) mice have no morphologically detectable caveolae in lung, intestine, and skeletal muscle, with diminished protein expression of all three caveolins, and exhibit glucose intolerance, dyslipidemia, and muscular dystrophy." (PMID 27612189, 2016).
colorectal cancer (8 papers, 2017 to 2025). A primary or metastatic malignant neoplasm that affects the colon or rectum. "Among signature-specific proteins, we followed-up Caveolae-Associated Protein-1 (CAVIN1) and demonstrated its role in tumor progression in a 3D in vitro model of colorectal cancer." (PMID 40269326, 2025). "PTRF, also named CAVIN1, is an unfavorable prognosis marker for ovarian, urothelial, and colorectal cancers, whereas SDPR (known as CAVIN2) is associated with a favorable prognosis in renal cancer and a poor prognosis in stomach cancer." (PMID 37775701, 2023). "This experiment revealed that, as expected, EMT-inducing cocktail increases invasiveness compared to WT cells, but most importantly, we observed that CAVIN1-KD abrogates the invasiveness potential of colorectal cancer cells." (PMID 40269326, 2025). "This protein, along with CAVIN-1, plays a role in inhibiting colorectal cancer progression and metastasis, with lower levels of CAVIN-1 indicating advanced disease stages." (PMID 39494346, 2024). "Therefore, we decided to investigate further if mTOR signaling in our colorectal cancer patient cohort in connection with CAVIN1 levels." (PMID 40269326, 2025). "Therefore, we decided to explore further the role of intra-tumor CAVIN1 levels in promoting invasiveness in colorectal cancer cell lines." (PMID 40269326, 2025). "The tissue specificity of CAVIN1/PTRF is relatively low, but it is expressed in mesenchymal cells, especially in adipose tissue, and has been reported as a prognostically unfavorable marker in urothelial cancer, ovarian cancer, and colorectal cancer." (PMID 36497311, 2022). "Therefore, future studies evaluating the involvement of CAVIN1 in drug resistance in colorectal cancer may provide further insights beyond our current findings." (PMID 40269326, 2025). "Nevertheless, most importantly, these results suggest a likely relationship between CAVIN1, EMT mechanisms and mTOR regulation in colorectal cancer." (PMID 40269326, 2025). "Therefore, we decided to evaluate CAVIN1 function not in the tumor microenvironment, but within the tumor cells, by using a 3D in vitro model of colorectal cancer." (PMID 40269326, 2025).
pancreatic cancer (7 papers, 2013 to 2025). "In this regard, CAVIN1 and other caveolae-associated proteins have been described as markers of poor prognosis in pancreatic cancer (where they modulated caveolin-1 function), glioblastoma, breast, or rhabdomyopsarcoae." (PMID 40269326, 2025). "This is consistent with previous studies linking CAVIN1 to metastatic potential in various tumor types, such as pancreatic cancer." (PMID 40269326, 2025). "Some observations point to Cavin-1 promoting tumor migration in pancreatic cancer cells by cooperating with caveolin-1 but inhibiting invasiveness and metastasis by matrix metalloproteinase 9 (MMP-9) production, neutralizing CAV1 tumor-promoting properties in PC3 pancreatic cancer cells." (PMID 35722492, 2022).
long QT syndrome (6 papers, 2010 to 2023). "Additionally, mutations in PTRF (Polymerase I and transcript release factor, or cavin-1) cause a particular form of congenital generalized lipodystrophy (type 4, CGL4) that is associated with features of long QT syndrome and high rate of sudden cardiac death." (PMID 28134617, 2017). "In patients with homozygous PTRF/Cavin-1 mutations, long-QT syndrome was observed." (PMID 27612189, 2016).
cardiomyopathy (5 papers, 2016 to 2024). A disease of the heart muscle or myocardium proper. "Congenital generalized lipodystrophy Type 4, caused by CAVIN1 mutations, is marked by atypical fat distribution, a milder metabolic phenotype, and cardiomyopathy." (PMID 39791064, 2024). "Importantly, these mechanisms could also contribute to biogenesis of T-tubules in the heart as Cav3, cavin 1 and cavin 4 mutations lead to cardiomyopathies." (PMID 37083699, 2023).
Glucose intolerance (5 papers, 2016 to 2023). Glucose intolerance (GI) can be defined as dysglycemia that comprises both prediabetes and diabetes. "Previous studies have reported that loss of CAVIN1 induced a reduction in numbers of caveolae, and CAVIN1 knockout mice demonstrated a lack of caveolae, glucose intolerance and disorders in lungs and cardiovascular system." (PMID 34513683, 2021).
lung cancer (5 papers, 2014 to 2026). A malignant neoplasm involving the lung. "AHNAK2, CAVIN1, and ODR4 have all been linked to metastatic processes in lung adenocarcinomas or non–small cell lung cancer, pointing to a potential overlap in functionality for homing or microenvironment adaptations." (PMID 41543394, 2026). "In detail, according to the different types of lung cancer, CAV1, CAV2, CAVIN1 and CAVIN2 had a dramatically lower expression in lung adenocarcinoma, squamous cell lung carcinoma and large cell lung carcinoma." (PMID 37497407, 2023).
melanoma (5 papers, 2014 to 2025). A malignant, usually aggressive tumor composed of atypical, neoplastic melanocytes. "We defined clusters corresponding to melanoma (PMEL, MLANA), immune infiltrates (TRBC2, TRAC, TMSB4X), melanophages (CD74, LYZ), keratinocytes (KRT14, TRIM29), blood vessels (CAVIN1, PECAM), and fibroblast‐enriched areas in the dermis (DCN, COL1A2, FBLN1)." (PMID 39846232, 2025).
non-small cell lung carcinoma (5 papers, 2012 to 2023). A group of at least three distinct histological types of lung cancer, including non-small cell squamous cell carcinoma, adenocarcinoma, and large cell carcinoma. "We have identified two proteins, PTRF/cavin-1 and MIF, which are differentially expressed between normal lung and non-small cell lung cancer." (PMID 22461895, 2012). "H1299 cells are a line of non-small cell lung carcinoma cells that lacked detectable cavin-3, but exhibited levels of cavin-1, caveolin-1, myosin-1c and actin that were similar to the endogenous levels of SV589 fibroblasts." (PMID 24069528, 2013).
Insulin resistance (4 papers, 2014 to 2024). Increased resistance towards insulin, that is, diminished effectiveness of insulin in reducing blood glucose levels. "Targeted mutations in PTRF/CAVIN-1 result in lack of caveolae in lung epithelium and, along with increases in insulin and free fatty acid levels, PTRF mutant mice show impaired glucose tolerance and insulin resistance." (PMID 24690998, 2014).
pulmonary hypertension (4 papers, 2014 to 2024). Increased pressure within the pulmonary circulation due to lung or heart disorder. "Such a mechanism was proposed to contribute to pulmonary arterial hypertension in cavin-1 deficient mice, but whether peripheral arteries are similarly affected has not been tested." (PMID 24658465, 2014). "Downregulation of Cavin-1 ameliorated CAV1 knockdown-induced pulmonary hypertension by recovering Smad 1/5/9 phosphorylation in PAECs." (PMID 38182755, 2024). "Cavin-1 knockdown reversed pulmonary hypertension and vascular remodeling induced by CAV1 knockdown." (PMID 38182755, 2024). "Functional studies on mice lacking cavin-1 are as yet scarce, but show that the mice exhibit a metabolic phenotype, and develop pulmonary arterial hypertension in association with mild changes of the cytoarchitecture in the lung." (PMID 24658465, 2014). "Furthermore, Cavin-1 knockdown is resistant to CAV1-induced pulmonary hypertension in vivo." (PMID 38182755, 2024). "Moreover, knockdown of cavin-1 renders it resilient to CAV1-driven pulmonary hypertension in vivo." (PMID 39507419, 2024). "Cavin-1 and BMPR2 competitively interact with the Caveolin-1 scaffolding domain that modulate BMP/Smad signal transduction in pulmonary artery endothelial cells and these interactions are involved in the development of pulmonary hypertension." (PMID 38182755, 2024).
acanthosis nigricans (3 papers, 2010 to 2025). A melanotic cutaneous lesion that develops in the axilla and other body folds. "Our second case of CGL4 with CAVIN1 mutation exhibited a generalized absence of fat, acanthosis nigricans, prominent facial musculature, pseudo-acromegaloid appearance, phlebomegaly in lower limbs, proximal myopathy, and achalasia cardia." (PMID 40718185, 2025).
asthma (3 papers, 2015 to 2023). "Polymerase 1 and transcript release factor (PTRF, encoding by Cavin-1) regulates interleukin 33 (IL-33) release, which is implicated in asthma development." (PMID 37454215, 2023).
atherosclerosis (3 papers, 2022 to 2025). A disease characterized by the build-up of fatty material and calcium deposition in the arterial wall resulting in partial or complete occlusion of the arterial lumen. "SAA has been shown to promote transendothelial LDL transcytosis via the NF-κB/caveolin-1/cavin-1 pathway during the pathophysiology of atherosclerosis." (PMID 41230093, 2025). "Recent evidence suggests that endothelial CAVIN-1 plays a pivotal role in the development and progression of atherosclerosis in mice." (PMID 36428375, 2022).
Ewing sarcoma (3 papers, 2016 to 2022). A small round cell tumor that lacks morphologic, immunohistochemical, and electron microscopic evidence of neuroectodermal differentiation.
liver diseases (3 papers, 2020 to 2025). "A mouse model with an endothelial specific knockout of Cavin1 is needed for further study on the roles of endothelial Cavin1 in liver diseases." (PMID 33042738, 2020).